MAL (mal, T cell differentiation protein (MAL blood group))
Diseases named in the same sentence as MAL in open-access papers (continued):
Sharing a sentence is not in itself a finding about the gene and the disease.
tumor (continued). "In conclusion, for MAL and probably for other genes in the family, dysregulation in cancer is a consequence of gene methylation, although CNAs and non-coding RNA contribute to varying degrees depending on the gene and the type of tumor." (PMID 37345137, 2023). "The epigenetic inactivation MAL, a tumor suppressor, is also a crucial biomarker in HNSCC." (PMID 36699376, 2022). "MAL provides insights into the pathophysiological process of GC, and its tumor suppressor function may be expected to become a novel therapeutic target in GC." (PMID 35093120, 2022). "Meanwhile, we also demonstrated that MAL, as a prognostic factor for WT, may be closely related to the tumor microenvironment." (PMID 35023304, 2022). "The role of methylation in MAL gene silencing was supported by restoring MAL mRNA levels in tumor cell lines after treatment with 5-aza-2′-deoxycytidine, which inhibits DNA methylation, combined or not with trichostatin A, which is an inhibitor of deacetylation." (PMID 33946345, 2021). "As a tumor suppressor gene, the promoter methylation of MAL has been found in CINs and CCs." (PMID 34323415, 2021). "We propose a model of MAL as the organizer of specialized condensed membranes to make them functional, discuss the role of MAL as a tumor suppressor in carcinomas, consider its potential use as a cancer biomarker, and summarize the directions for future research." (PMID 33946345, 2021). "The analyses of the methylation status of MAL in normal cells and in a number of tumor specimens and tumor-derived cell lines indicate that the MAL CpG island is the subject of methylation, and that this epigenetic mechanism contributes to the downregulation of MAL gene expression in many cancers." (PMID 33946345, 2021). "Interestingly, the relative expression level of MAL was significantly elevated in tumor tissue than in normal tissue." (PMID 32099532, 2020). "Interestingly, the relative expression level of MAL was significantly elevated in tumor tissues compared to the normal tissues." (PMID 32099532, 2020). "In addition, 81.58% of the primary tumors in T1/T2 stages had weak staining for MAL, whereas of 12 tumor cases in T3/T4 stages, only 1 (8.33%) had weak reactions for MAL." (PMID 27029067, 2016). "Another group has shown that tumor-derived exosomal miR-494 and miR-542-3p were able to modify distant lymph nodes and lung tissue toward a pre-metastatic phenotype suitable for tumor cell hosting, by targeting cdh17 and MAL, and cdh17 and TRAF4, respectively." (PMID 26258125, 2015). "When prior available MAL and bcl-2 expression data are included in a multivariate analysis of all clinical and biologic factors, a FOXP3/GrB ratio of 1 or less and tumor cell expression of MAL and bcl-2 all independently predicted poor failure-free survival (FFS)." (PMID 22151904, 2011). "As such, our study strongly suggests that the MAL gene may be a candidate tumor suppressor in HNSCC and a potential and novel therapeutic target for HNSCC." (PMID 21092172, 2010). "IL1RN, MAL and MMP1 are prospective tumor diagnostic markers for HNSCC." (PMID 19835631, 2009). "Methylated ADAMTS1, MGMT, and MAL are suitable as markers for early tumor detection." (PMID 19117505, 2008). "Furthermore, RNA and/or protein expression levels of MAL were determined in in vivo tumours as well as in in vitro models, the latter also including various cancer types." (PMID 18346269, 2008). "Finally, MAL has been shown to possess tumour suppressor capabilities by suppressing motility, invasion, and tumorigenicity and enhance apoptosis in oesophageal cancer." (PMID 18346269, 2008). "Thus, the MAL gene happens to be a robust candidate tumour suppressor gene." (PMID 38461243, 2024). "Thus, exogenously-expressed MAL in breast, esophageal, cervical, colorectal, lung, and head and neck cancer cell lines reduced cell migration and invasion, or increased apoptosis, and reduced tumor size in nude mice." (PMID 37345137, 2023).
tumor (continued). "However, the expression of MAL in primary tumor tissues was substantially downregulated." (PMID 35093120, 2022). "However, CD44 was upregulated and MAL was significantly downregulated in tumor tissues." (PMID 35093120, 2022). "MAL is involved in the apical transport of proteins in polarized epithelial cells; however, apart from the role of MAL in apical sorting and its function as a raft stabilizer, researchers have not clearly determined the mechanism by which MAL regulates the development of tumor cells." (PMID 35093120, 2022). "MAL may have a tumor suppressive role in some cancers and an oncogenic role in others." (PMID 33946345, 2021). "Myelin and lymphocyte protein (MAL), MAL2, MAL like protein (MALL, formerly BENE) are involved in several human cancers 23,118,119, either promoting or suppressing tumor growth and metastasis 120-122." (PMID 37928877, 2023). "MAL mediates the mesenchymal transition of GC cells by inhibiting the STAT3 pathway, thereby regulating the proliferation, metastasis and invasion of tumor cells." (PMID 35093120, 2022). "First of all, we obtained hub genes by taking the intersection between DEGs of TCGA and GEO,finding that BCHE, MAL and ASPM are tumor-related genes and can be used as potential biomarkers in EC treatment." (PMID 32099532, 2020). "Using UALCAN, we found that MAL and ASPM expressed higher in tumor than in normal tissues, both negatively related to the overall survival of the EC patients." (PMID 32099532, 2020). "For urine supernatant, there was a significant correlation between methylation levels of MAL, PHACTR3, PRDM14, SST and ZIC1 and the matched tumor tissues." (PMID 32252299, 2020). "Cluster A contained 12 tumours and was characterised by high GSTP1 methylation and MAL methylation and relatively lower RASSF1A methylation." (PMID 28893223, 2017). "The established activities of DYPS, MAL, and TIG1 are consistent with tumor suppression while CCND2, HSPB1 and PITX2 are mainly oncogenic." (PMID 27708246, 2016). "Our study grants further investigations of the functional connections between MAL/MRTF family members and tumor suppressors such as Eplin-α during cancer progression." (PMID 20236507, 2010). "These levels were lower in tumor than in normal samples for KRT4, KRT13, IL1RN, MAL and TGM3 (Wilcoxon test for paired data, p < 0.001)." (PMID 19835631, 2009). "MAL and MUC1 showed an antagonistic relationship in cancer cells, and these findings provide new insights with respect to the regulation of MUC1 and a better understanding of MAL as a potential tumor suppressor." (PMID 42038033, 2026). "Given the very high level of expression of MAL in normal esophageal mucosa and its dramatic downregulation in ESCA, monitoring MAL expression by IHC could be useful for characterizing incipient neoplasms in esophageal biopsies." (PMID 37345137, 2023). "In conclusion, our results were in accordance with the earlier research, the MAL expression was decreased in HNSCC patients, indicating that the MAL gene may be a new candidate tumor-suppressor gene for HNSCC." (PMID 37185487, 2023). "Because STAT3 regulates tumor progression, we next verified whether STAT3 was involved in MAL-mediated inhibition of the EMT in GC cells." (PMID 35093120, 2022). "In addition, we performed CD44 and MAL costaining of these samples and found similar expression patterns for MAL; CD44, a tumor stem marker, was expressed at low levels in early GC and at high levels in advanced GC." (PMID 35093120, 2022). "A few studies have compared nude mice inoculated subcutaneously with tumor cells that did or did not express exogenous MAL, and found the tumor to be of smaller volume in the former group." (PMID 33946345, 2021). "BCHE, MAL and ASPM are tumor-related genes and can be used as potential biomarkers in EC treatment." (PMID 32099532, 2020). "The candidate tumor suppressor genes were ZBTB16, MAL, LIFR, and SLIT2." (PMID 33193630, 2020).
tumor (continued). "The tumor suppressor genes were ZBTB16, MAL, LIFR, and SLIT2." (PMID 33193630, 2020). "Human chemokine like factor (CKLF)-like MAL and related proteins for vesicle trafficking transmembrane, domain-containing member 5 (CMTM5) has been shown to involved and may function as a tumour suppressor in tumorigenesis." (PMID 29213215, 2017). "Eleven cancer related genes were found to have methylation (defined as more than 10 % methylation) in at least some of the tumours: RASSF1A (64 %), TWIST1 (61 %), CDH13 (51 %), APC (50 %), MAL (35 %), GSTP1 (30 %), WIF1 (26 %), RARβ (19 %), BRCA1 (2 %), CDKN2A (2 %) and TP73 (2 %)." (PMID 26452468, 2015). "However, methylation-driven silencing of MAL promoter takes place at a very early point, before HPV-positive keratinocytes undergo tumor transformation." (PMID 23781508, 2013). "To evaluate whether MAL functions as a tumor suppressor in HNSCC cells, we assessed the effect of MAL expression on cell proliferation and colony formation." (PMID 21092172, 2010). "The results showed that tumor growth was significantly reduced in MAL-expressing (clone #12) cells as compared to MAL-non-expressing (clone #6) cells (P < 0.05)." (PMID 21092172, 2010). "In addition, MAL reduces mitochondrial membrane potential and promotes mitochondrial-mediated apoptosis through the BAX/Bcl-2/caspase-3 axis, further amplifying endogenous apoptosis in tumor cells." (PMID 41669875, 2026). "It is clear is that the proposed role of MAL as a tumor suppressor does not extend to all types of cancer, and malignancies of hematological cell types in which MAL is endogenously expressed, and at least those of the ovarian epithelium, are specifically excluded." (PMID 33946345, 2021). "The TNM stage of patients may be easy to obtain, while the acquisition of another predictor (risk score) required knowledge of the expression of four immune-related genes (MAL, MS4A1, OAS1, and WFDC2) in tumor tissues, which undoubtedly increased the burden of nomogram application." (PMID 32850406, 2020). "Additionally, tumor growth was suppressed in cells expressing MAL as compared with cells not expressing MAL." (PMID 21092172, 2010). "Therefore, tumours without MAL methylation might have a different biology overall, which could relate to poorer clinical outcome, rather than the outcome being dependent on MAL itself." (PMID 19002170, 2008). "Our results indicated opposite expression patterns for MAL and CD44 in matched primary tumor samples, indicating a negative correlation in vivo." (PMID 35093120, 2022).
cancer (44 papers, 2008 to 2026). A tumor composed of atypical neoplastic, often pleomorphic cells that invade other tissues. "One study reported that MAL expression increased in chemo-resistant cancers, and is associated with short overall survival." (PMID 38248716, 2023). "We observed a significant association between MAL promoter methylation and BC (p=0.01), after adjusting for age, family history of cancer and DRC." (PMID 24927296, 2014). "In this regard, the MAL (myelin and lymphocyte protein) gene, implicated in conferring resistance to cancer therapy, is differentially upregulated in short-term survivors (three-fold increase compared with long-term survivors and 29-fold increase compared with early-stage patients)." (PMID 27382614, 2014). "In any case, while the lack of MAL might result in the loss of compaction of important platforms involved in signaling and trafficking, thereby causing their dysregulation, the excess of MAL could further compact those platforms in such a way that facilitates cancer progression." (PMID 33946345, 2021). "Incorporating anti-MAL antibodies into current antibody panels to detect MAL, either in biopsies or, as a non-invasive procedure, in human body fluids or waste matter, might provide a prognostic/diagnostic tool for cancer patients that can be used in routine clinical practice." (PMID 33946345, 2021). "The best diagnostic performance for carcinoma was achieved with the combined methylation analysis of CADM1 and MAL (AUC = 0.912), which outperformed the individual markers: CADM1 (AUC = 0.770), MAL (AUC = 0.770), and PAX1 (AUC = 0.813)." (PMID 40564169, 2025). "MAL methylation was highly specific for carcinoma, whereas PAX1 methylation appeared earlier in the disease course, suggesting its potential utility for detecting precancerous changes." (PMID 40564169, 2025). "MAL methylation was detected exclusively in carcinoma samples, supporting its potential utility as a late-stage marker." (PMID 40564169, 2025). "Among the tested biomarkers, the combined methylation panel of CADM1/MAL exhibited the highest diagnostic performance for distinguishing histologic HSIL+ and carcinoma from low-grade lesions and NILM." (PMID 40564169, 2025). "The mRNA expression levels of MAL were significantly different between cancer tissue and normal tissue; they were downregulated in 18 cancers and upregulated in 12 cancers." (PMID 40625454, 2024). "Reports about promoter methylation of MAL-family genes in cancer are available only for MAL, MAL2, and MALL." (PMID 37345137, 2023). "This review uses these two sources to investigate the expression of the MAL gene family in cancer and to explore their potential biomedical applications as cancer biomarkers." (PMID 37345137, 2023). "There is sparse published information about the expression of MAL gene family members in cancer and their use as cancer biomarkers." (PMID 37345137, 2023). "The level of gene methylation can affect the expression of genes, and methylation of MAL has been extensively demonstrated in a variety of cancers." (PMID 35023304, 2022). "In this study, we performed CD44 and MAL costaining in the collected GC samples to identify the level of the MAL protein in cancer cells expressing stemness markers as a method to assess the relationship between MAL protein levels and cancer stemness." (PMID 35093120, 2022). "STAT3 plays a key role in signal transduction pathways of cancer stem cells, and we found that MAL overexpression inhibited STAT3 phosphorylation in GC cells and MAL knockdown increased STAT3 phosphorylation." (PMID 35093120, 2022). "MAL not only inhibited the progression of cancer, but in some cases, it also promoted the development of cancer." (PMID 35023304, 2022). "We verified the function of MAL in the GC process using two human GC cell lines and found that MAL hinders the proliferation, metastasis and invasion of cancer cells." (PMID 35093120, 2022).
cancer (continued). "Unfortunately, compared with other markers, there are few immunohistochemical assessments of MAL expression in large numbers of cancer specimens." (PMID 33946345, 2021). "In some studies, the ability of exogenously expressed MAL to inhibit processes related to cancer progression, such as enhanced migration, invasion or tumorigenicity, was also analyzed to confirm the involvement of MAL in the malignant phenotype." (PMID 33946345, 2021). "In the prostate, MAL was identified as one of six genes whose methylation is a strong predictor of aggressive cancer in patients categorized in the group of low-to-intermediate risk disease." (PMID 33946345, 2021). "The role of MAL as a receptor for the Clostridial epsilon toxin, the epigenetic regulation of MAL gene expression in cancer, and the use of MAL as a cancer biomarker are also discussed." (PMID 33946345, 2021). "Here, EV-associated miRNAs regulate the expression of cadherin-17, MAL (Myelin And Lymphocyte protein) and TRAF4 (TNR Receptor-Associated Factor 4) genes, leading to the upregulation of matrix metalloproteases, thus facilitating cancer cell migration." (PMID 31817101, 2019). "SCAI (suppressor of cancer cell invasion) has been recently characterized as a protein that inhibits the invasive migration of human tumor cells through the control of MAL/SRF signaling." (PMID 23936361, 2013). "We have recently characterized SCAI (Suppressor of Cancer Cell Invasion), a transcriptional modulator regulating cancer cell motility through suppression of MAL/SRF dependent gene transcription." (PMID 23936361, 2013). "In the present study, hypermethylated MAL was found in cancer cell lines from breast, kidney, ovary, and uterus." (PMID 18346269, 2008). "The result showed that MAL was detected in the lymphoid cells of the cancer stroma." (PMID 40612871, 2025). "In contrast, CADM1 and MAL showed no significant diagnostic value for carcinoma detection in this context." (PMID 40564169, 2025). "MAL is also defined as a tumor suppressor gene in many cancers." (PMID 36010947, 2022). "In addition, Stattic also inhibited the increases in cancer cell metastasis and invasion after interfering with MAL expression." (PMID 35093120, 2022). "In this regard, although MAL KO mice appear normal in general and have a normal life span, it will be interesting to compare whether they are more prone to developing cancer than wild-type mice when treated with carcinogens." (PMID 33946345, 2021). "Given the role of polarity loss in cancer cell metastasis, further studies will assess whether MALL influences apical transport in a similar fashion as MAL." (PMID 26992238, 2016). "Based these data and findings in other cancers, we proposed that DNA hypermethylation of the MAL regulatory elements could be a major contributor to the downregulation of MAL in HNSCC." (PMID 21092172, 2010). "However, the previous studies indicated that DNA methylation level of MAL promoter was increased in various types of carcinoma." (PMID 21092172, 2010). "The previous reports also described the similar down-modulation of MAL gene expression in certain cancer types, indicating MAL gene downregulation might be as a common molecular event contributing to initiation and/or progression of cancers." (PMID 21092172, 2010). "Furthermore, the Annexin V-PE and 7-AAD staining, along with the increasing cell population in sub-G1 phase and elevating cleaved PARP level revealed that the inhibitory effect of MAL on cell proliferation was through intensively inducing early apoptosis of cancer cells." (PMID 21092172, 2010). "Moreover, it has been proposed as a candidate marker for early detection of these cancers, as methylation of MAL could already be detected in precursor lesions." (PMID 19002170, 2008).